LINC01234 (long independently transcribed non-coding RNA 1234)
Diseases named in the same sentence as LINC01234 in open-access papers (continued):
Sharing a sentence is not in itself a finding about the gene and the disease.
cancer (17 papers, 2014 to 2024). A tumor composed of atypical neoplastic, often pleomorphic cells that invade other tissues. "It is also important to highlight bioinformatics analysis revealed that LINC01234 is involved in cancer‐associated pathways such as cell cycle and mismatch repair." (PMID 32011780, 2020). "We verified that LINC01234 expression levels were increased in cancer tissues and BC cell lines and that upregulation of LINC01234 was associated with poor prognosis of BC." (PMID 35923244, 2022). "LINC01234 is considered to be related to the drug resistance of cancer patients, and a study displayed that LINC01234 can increase the resistance of cancer cells to chemotherapeutic drugs by regulating the LINC01234/miR-31-5p/MAGEA3 axis." (PMID 33585468, 2020). "In summary, our results suggested that Linc01234 plays a cancer-promoting role in cell growth and metastasis in OSCC." (PMID 32041570, 2020). "Recent studies showed that LINC01234 promotes cancer development as a miRNA sponge and can regulate multiple miRNAs, including miR-27b-5p, miR-525-5p, miR-106b, miR-193a-5p, miR-433, miR-340-5p and miR-27b-3p, miR-1284, miR-637, miR-140, miR-642a-5p, and miR-204-5p." (PMID 35923244, 2022). "Collectively, the data above suggested that LINC01234 exerts cancer promoting factors in ACC." (PMID 35765893, 2022). "LINC01234, located on chromosome 12, plays an active role in several cancers." (PMID 35923244, 2022). "Among them, LINC01234 has been reported to be involved in the biological processes of some cancers." (PMID 33869028, 2021). "However, whether LINC01234 displays similar functions, mechanisms of action, and targets in other cancers is unknown and should be investigated in the future." (PMID 31959200, 2020). "Various lncRNAs such as LINC00857, MIR17HG, NKX2-1-AS1, LINC01234, and FAM225A have been found to manipulate specific miRNAs to influence cancer cell behavior." (PMID 39172101, 2024). "Over the past decade, an increasing number of lncRNAs have been shown to drive cancer metastasis, such as lncRNA HOXA11-AS and LINC01234." (PMID 36418856, 2022). "To explore the potential functions of LINC01234 in GC, we firstly divided the STAD patients from TCGA into two groups, low expression and high expression of LINC01234 in cancer tissues, respectively." (PMID 32011780, 2020).
LINC01234 also shares sentences with these, for which no sentence is quoted: colorectal cancer (4 papers); multiple myeloma (2); adrenocortical carcinoma (1); bladder cancer (1); colorectal adenocarcinoma (1); glioblastoma multiforme (1); kidney cancer (1); lung squamous cell carcinoma (1); nasopharyngeal carcinoma (1); oral cancer (1); osteosarcoma (1); ovarian carcinoma (1); pancreatic carcinoma (1); prostate carcinoma (1); renal carcinoma (1); stomach adenocarcinoma (1).